TRPM2 (transient receptor potential cation channel subfamily M member 2)
Diseases named in the same sentence as TRPM2 in open-access papers (continued):
Sharing a sentence is not in itself a finding about the gene and the disease.
Anxiety (4 papers, 2021 to 2025). Intense feelings of nervousness, tension, or panic often arise in response to interpersonal stresses. "Using TRPM2 KO mice, Jong and colleagues demonstrated that loss of TRPM2 is associated with the behavioral manifestations of BD, including increased anxiety and impaired social interaction." (PMID 37576339, 2023). "The findings of this study also suggest that TRPM2 and its interaction with IEGs could offer novel targets for therapeutic strategies in anxiety and trauma-related disorders, such as PTSD." (PMID 40016847, 2025). "Decreased anxiety-like behaviorNon-stressed TRPM2 KO mice show less latency to feed compared with non-stressed WT in novelty suppressed feeding test.Non-stressed TRPM2 KO mice show less immobility time compared with non-stressed WT in forced swim test." (PMID 33644051, 2021).
brain injury (4 papers, 2016 to 2025). Acute and chronic (see also brain INJURIES, CHRONIC) injuries to the brain, including the cerebral hemispheres, CEREBELLUM, and brain STEM. "A recent study suggests that ischemic insults triggers the release of endogenous bilirubin from injured cells, which activates the transient receptor potential melastatin 2 (TRPM2) channels and aggravates Ca2+-dependent brain injury." (PMID 38651104, 2024).
injury (4 papers, 2017 to 2023). Damage inflicted on the body as the direct or indirect result of an external force, with or without disruption of structural continuity. "The pathogenesis of APAP-mediated acute liver injury involves the activation of TRPV1, TRPV4, TRPC1, TRPM2, and TRPM7 channels, which trigger the influx of Ca2+ into hepatocytes and subsequent cellular damage." (PMID 37569884, 2023).
Listeria infection (4 papers, 2020 to 2025). "In vivo, Trpm2-/- CD8+ T cells show regular responses in the Listeria monocytogenes infection model both after infection of Trpm2-/- mice and after transfer of deficient T cells into infected recipients." (PMID 35095852, 2021). "In the present study, we use a mouse model of Listeria monocytogenes infection to define the role of TRPM2 in the regulation of neutrophils' functions during infection." (PMID 32117251, 2020). "In conclusion, our findings suggest that the TRPM2 channel plays critical functional roles in regulating the inflammatory properties of neutrophils and preventing tissue damage during Listeria infection." (PMID 32117251, 2020). "In order to analyze the role TRPM2 in CD8+ T cells in vivo, we used the Listeria monocytogenes infection model." (PMID 35095852, 2021).
lung adenocarcinoma (4 papers, 2013 to 2024). A carcinoma that arises from the lung and is characterized by the presence of malignant glandular epithelial cells. "Using GEPIA database, we found that the expression of TRPM2 in tumor was higher than that of normal tissues and predicted a poor prognosis of lung adenocarcinoma patients." (PMID 34226519, 2021). "Analysis of TCGA data showed that TRPM2, among the TRP genes, was the only one whose expression was significantly increased in human lung adenocarcinomas (LUAD) compared with normal tissues and its high expression was significantly associated with the poor survival of patients with EGFRm NSCLC." (PMID 39044361, 2024).
metastatic melanoma (4 papers, 2015 to 2025). A melanoma that has spread from its primary site to another anatomic site. "Accordingly, our recent study demonstrated selective anticancer effects in human metastatic melanoma cells due to the antagonism of TRPM2." (PMID 37445615, 2023). "Two TRPM2 mRNA transcripts, one antisense transcript and one truncated TRPM2 transcript were shown to be increased in metastatic melanoma cell lines." (PMID 26178079, 2015). "Our recent study reported a nuclear localization of full-length TRPM2 in three lines of human metastatic melanoma cells, while localization in noncancerous skin cells exhibited a cytoplasmic/plasma membrane localization." (PMID 37445615, 2023). "In order to test whether the high expression and functionality of KCNMA1, KCNN4, and TRPM2 is specific to (primary) IGR39 cells, we analyzed several publicly available datasets on gene expression in melanocytes, as well as primary and metastatic melanoma cell lines." (PMID 34445066, 2021).
pancreatic ductal adenocarcinoma (4 papers, 2021 to 2022). An infiltrating adenocarcinoma that arises from the epithelial cells of the pancreas. "Transient receptor potential cation channel subfamily M member 2 (TRPM2) levels were increased in patients with pancreatic ductal adenocarcinoma with increasing tumor stage and showed a negative correlation with overall and progression-free survival time." (PMID 36358843, 2022).
renal fibrosis (4 papers, 2020 to 2025). A final common manifestation of a wide variety of chronic kidney diseases characterized by glomerulosclerosis and tubulointerstitial fibrosis. "Suppression of TRPM2 expression has been shown to reduce renal fibrosis induced by unilateral urethral obstruction, and suppress inflammatory cell infiltration and release of pro‐inflammatory factors." (PMID 33237659, 2021). "Related to this, it was shown that TRPM2 activity is involved in renal fibrosis through JNK pathway activation." (PMID 33291725, 2020). "The modulation of TRPM2 by tart cherry could be explained by the observed reduction in renal fibrosis and inflammation in obese rats." (PMID 41009007, 2025). "As an identified nonselective Ca2+-permeable cation channel and the sensor of ROS (causing cell damage by elevating intracellular calcium content under oxidative stress), TRPM2 has been recently demonstrated as being involved in the unilateral ureteral obstruction (UUO)-triggered renal fibrosis." (PMID 33291725, 2020). "On the other hand, other studies have found that TRPM2 suppression (which reduces inflammation and renal fibrosis by blocking TGF-β1-regulated JNK activation) might be a possible therapeutic target in renal fibrosis and chronic kidney disease prevention." (PMID 33291725, 2020).
T-cell leukemia (4 papers, 2016 to 2023). A malignant disease of the T-lymphocytes in the bone marrow, thymus, and/or blood. "Here, we analyzed the crosstalk between Bcl-2 and TRPM2 channels in T cell leukemia cells during oxidative stress as conferred by ionizing radiation (IR)." (PMID 26839633, 2016). "Collectively, this data suggests a pivotal function of TRPM2 in the DNA damage response of T cell leukemia cells." (PMID 26839633, 2016). "TRPM2 inhibition also leads to increased DNA damage and cytotoxicity in triple-negative or estrogen-receptor-positive breast cancer, reducing survival and restrain migration of tongue carcinoma, and enhancing the radiation sensitivity in T-cell leukemia." (PMID 37608401, 2023).
vitiligo (4 papers, 2019 to 2025). Generalized well circumscribed patches of leukoderma that are generally distributed over symmetric body locations and is due to autoimmune destruction of melanocytes. "Of note, the elevated level of TRPM2 expression in vitiligo skin suggests this mechanism as a possible facilitator of vitiligo melanocyte loss." (PMID 41007740, 2025). "TRPM2 is sensitive to oxidative stress and is found to be overexpressed in lesional melanocytes of vitiligo." (PMID 38542277, 2024). "Another study explored the role of transient receptor potential cation channel subfamily M member 2 (TRPM2) overexpression in the pathogenesis of vitiligo." (PMID 38542277, 2024). "A recent study indicated that TRPM2, a Ca2+ channel sensitive to oxidative stress, is upregulated in vitiligo melanocytes and that its inhibition in normal epidermal cells prevents Ca2+ influx, ROS accumulation, and apoptosis induced by oxidative stress." (PMID 31866583, 2019). "Clinical and biochemical studies suggest that the overexpression of the TRPM2 gene (transient receptor potential cation channel subfamily M member 2) and the CGRP (calcitonin gene-related peptide) peptide are related to OS-sensitive calcium channels in perilesional melanocytes in vitiligo." (PMID 35643735, 2022).
asthma (3 papers, 2013 to 2022). "The same group claiming TRPM2 expression in lysosomes also explored the relevance of TRPM2 in severe asthma pathophysiology since airway inflammation and asthma are linked to oxidative stress." (PMID 35053420, 2022). "In this study, we investigated the role of TRPM2 channels in the pathophysiology of severe asthma by using TRPM2-deficient mice in a model of OVA-induced inflammatory airway disease." (PMID 23631390, 2013). "Given that airway inflammation and asthma have been linked to oxidative stress, we investigated whether TRPM2, a Ca2+-permeable ion channel involved in ROS signaling, contributes to pathophysiology." (PMID 23631390, 2013). "Airway inflammation and asthma have been linked to oxidative stress and the melastatin-related transient receptor potential cation channel, member 2 (TRPM2), which can be activated by reactive oxygen species (ROS), has emerged as a potential therapeutic target for inflammatory diseases." (PMID 23631390, 2013). "In most of the cells, TRP channels are expressed, and strong evidence for an essential role in airway function and associated diseases, such as CF, asthma, fibrosis and edema was demonstrated for TRPA1, TRPC6, TRPM2, TRPM5, TRPM7, TRPV2, TRPV4 and TRPV6." (PMID 36139480, 2022). "For this, we analyzed the inflammatory allergic reaction of WT and TRPM2-/- mice in an OVA-induced severe asthma model." (PMID 23631390, 2013). "In the present study, we assessed the role of TRPM2 channels in airway inflammation by using an experimental OVA-induced severe asthma model." (PMID 23631390, 2013). "Nevertheless, further investigations using a less severe asthma model are needed to fully address the role of TRPM2 in lung inflammation." (PMID 23631390, 2013). "To further evaluate whether TRPM2 contributes to airway inflammation and severe asthma, we examined whether the recruitment of inflammatory cells into the lungs was affected in the absence of TRPM2 channels." (PMID 23631390, 2013). "However, the relevance of TRPM2 in severe asthma pathophysiology has not yet been explored." (PMID 23631390, 2013).
bladder cancer (3 papers, 2017 to 2020). "For example, TRPM2 overexpression promoted apoptosis of T24 bladder cancer cells; survival time was significantly longer in patients with higher TRPM2 levels than in those with lower TRPM2 levels." (PMID 33092205, 2020). "It has been shown that HDAC inhibition induced apoptosis via upregulation of TRPM2 (Transient receptor potential cation channel, subfamily M, member 2) expression in bladder cancer cells." (PMID 29096636, 2017).
breast tumors (3 papers, 2015 to 2025). "Recent studies have demonstrated elevated expression of transient receptor potential melastatin 2 (TRPM2) channels in breast tumor tissues." (PMID 41306344, 2025). "Thus, our results offer the possibility that targeting TRPM2 in breast tumors refractive to chemotherapeutic treatments may lead to the improved eradication of such tumors." (PMID 26178079, 2015).
colon cancer (3 papers, 2022 to 2025). "Two known TRPM2 inhibitors, 2-APB and CLT, were tested in human colon cancer cell HCT116, colorectal adenocarcinoma cell SW480 and renal cancer cell ACHN." (PMID 37649595, 2023).
colorectal cancer (3 papers, 2020 to 2025). A primary or metastatic malignant neoplasm that affects the colon or rectum. "TRPM2-expression also predicted survival outcomes in breast, lung, or colorectal cancers." (PMID 36046118, 2021).
Fever (3 papers, 2019 to 2023). Body temperature elevated above the normal range. "The strong temperature dependence of TRPM2 activation suggests a novel function for fever: by enhancing TRPM2 activation, fever potently enhances the sensitivity to a gradient of H2O2, thereby enhancing neutrophil guidance and promoting the detection and killing of invading pathogens." (PMID 33927223, 2021). "However, SHANK3 or/and TRPM2 play an important role in maintaining body temperature, under stressful conditions with temperature perturbations, such as LPS challenge, VNS by auricular application of menthol and capsaicin, cold environment, and PGE2-induced fever." (PMID 36845137, 2023).
fibrosis (3 papers, 2019 to 2025). the formation of excess fibrous connective tissue in an organ or tissue in a reparative or reactive process. "Irradiated TRPM2-deficient mice developed less inflammation, fewer severe skin lesions and decreased fibrosis when compared to wild type mice." (PMID 30483886, 2019). "Furthermore, histological analysis of skin lesions showed that TRPM2-deficiency protected the tissue from irradiation-induced damage by limiting the inflammation and the development of fibrosis in irradiated skin." (PMID 30483886, 2019).
Hypercholesterolemia (3 papers, 2022 to 2025). An increased concentration of cholesterol in the blood. "Adeno-associated virus (AAV)-mediated overexpression of PCSK9 was used to induce hypercholesterolemia to elicit atherosclerotic development in TRPM2+/+ and TRPM2−/− mice." (PMID 35563730, 2022).
major depressive disorder (3 papers, 2020 to 2023). An episode of depression lasting two or more weeks without an intervening episode of mania. "Other findings expand the likely effects of TRPM2 channels to include major depressive disorders, as well as other behavioral phenotypes that are related to oxidative stress." (PMID 36902145, 2023).
mental disorder (3 papers, 2014 to 2021). A disease that has its basis in the disruption of mental process. "On the other hand, accumulating evidence implicates that the TRPM2 channels as an oxidative stress sensor is also related to these mental disorders." (PMID 25386648, 2014). "Finally, TRPM2 may be a new target for modulating social stress and in psychiatric disorders with social impairment." (PMID 27499729, 2016).
migraine (3 papers, 2024 to 2026). "The relative role of neuronal and immune TRPM2 in migraine remains to be defined." (PMID 41511359, 2026). "Inhibition of TRPM2 upregulation by gastrodin, a bioactive compound from the traditional Chinese medicine Gastrodia elata Blume (GEB), prevented migraine." (PMID 41511359, 2026). "In the glyceryl trinitrate (GTN) migraine mice model, GTN increased the production of ROS and cytokines (IL-1β, IL-6 and TNFα) and enhanced TRPM2 expression and function in TG neurons." (PMID 41511359, 2026). "TRPM2 blockers (N‐(p‐amycinnamoyl) anthranilic acid (ACA) and 2‐aminoethoxydiphenyl borate (2‐APB)) and Trpm2 knockout reduce migraine‐like pain behaviors." (PMID 41399206, 2025). "In particular, activated TRPA1, TRPM2, TRPM8, and TRPV1 channels participate in migraine progress through amplifying neuroinflammation." (PMID 41399206, 2025). "Furthermore, TRPM2 blockers (N-(p-amylcinnamoyl)anthranilic acid (ACA) and 2-aminoethoxydiphenyl borate (2APB)) inhibited mechanical and heat hyperalgesia in the GTN migraine mice model." (PMID 41511359, 2026).
thyroid cancer (3 papers, 2020 to 2023). "Indeed, TRPM2, TRPM7, TRPM8, TRPV2, and TRPC1 have shown to cause upregulation of MMP9 in a Ca2+-dependent manner in gastric, bladder, oral squamous, prostate and thyroid cancer cells respectively." (PMID 33132914, 2020). "Additionally, TRPM2, TRPM7, and TRPC1 activity have been also correlated with MMP2 production in gastric, lung, pancreatic and thyroid cancer." (PMID 33132914, 2020). "No significant alteration of TRPM2 mRNA expression was observed in Kidney Chromophobe (KICH) and Thyroid carcinoma (THCA)." (PMID 37608401, 2023).
viral disease (3 papers, 2022 to 2025). "Overexpression of JAK1, TYK2, MAP2K1, IFNG, TRPM2, and ADCY9 significantly inhibited viral infection, whereas overexpression of SNX27, GATA4, EHMT2, PCBP2, SMARCA4, and SLX4 enhanced viral infection." (PMID 40530850, 2025).
brain infarct (2 papers, 2024 to 2025). "In another study, TRPM2 was specifically deleted in neurons, and authors reported reduced brain infarct volume and neuronal death in an ischemic mouse model, but they did not evaluate neuroinflammation." (PMID 40665621, 2025). "Studies have also demonstrated that genetic deletion of TRPM2 can alleviate hypoxic-ischemic brain injury in neonatal mice, characterized by reduced post-I/R cerebral infarct size and improved sensorimotor deficits." (PMID 39007141, 2024).
cardiac arrest (2 papers, 2021 to 2024). Cessation of breathing and/or cardiac function. "Our strategy of targeting persistent engagement of TRPM2 channels in surviving neurons in a network weeks after cardiac arrest offers a novel strategy to reverse learning and memory deficits induced by global cerebral ischemia." (PMID 34659399, 2021).
clear cell renal cell carcinoma (2 papers, 2023). "Of human TRP genes, TRPM2 shows the highest expression in conventional (clear cell) renal cell carcinoma (ccRCC)." (PMID 37240443, 2023).
cognitive decline (2 papers, 2024 to 2025). "Nonetheless, the data presented here provides evidence for improved synaptic and memory function following severe TBI, implicating TRPM2 channels in TBI-induced cognitive decline." (PMID 40352737, 2025). "TRPM2 (transient receptor potential melastatin 2) deletion can protect mice from CPZ-induced demyelination, synaptic loss, microglial activation, NLRP3 inflammasome activation, and pro-inflammatory cytokine production, ultimately ameliorating cognitive decline." (PMID 39710713, 2024).
diabetic neuropathy (2 papers, 2023 to 2026). A chronic, pathological complication associated with diabetes mellitus, where nerve damages are incurred due to diabetic microvascular injury involving small blood vessels that supply these nerves, resulting in peripheral and/or autonomic nerve dysfunction. "Additionally, the study investigated the activation of the TRPM2 channel in the mechanism underlying sciatic nerve injury of diabetic neuropathy rat model using the ELISA method." (PMID 38234970, 2023). "Bayir and coworkers explored the potential of hesperidin in alleviating diabetic neuropathy and elucidating the role of the transient receptor potential melastatin 2 (TRPM2) channels in this process." (PMID 38234970, 2023). "Based on the findings, it appears that hesperidin has a regulatory impact on increased reactive oxygen species (ROS), Poly (ADP-ribose) polymerase (PARP) 1, and activation of the TRPM2 channel in the sciatic nerves of rats modeled with diabetic neuropathy." (PMID 38234970, 2023).
gastric tumor (2 papers, 2019 to 2023). "Overall, these data indicate that TRPM2 downregulation inhibits in vivo gastric tumor growth and reverses the EMT process which further confirmed our findings on the role of a TRPM2 ion channel in GC progression." (PMID 30862883, 2019).
heart failure (2 papers, 2024 to 2025). Inability of the heart to pump blood at an adequate rate to meet tissue metabolic requirements. "Compared with healthy hearts, the expression of TRPM2 is significantly reduced in the cardiac tissues of patients with heart failure, indirectly supporting the hypothesis that TRPM2 has a cardioprotective effect." (PMID 39007141, 2024).